MAP2 (microtubule associated protein 2)
Diseases named in the same sentence as MAP2 in open-access papers (continued):
Sharing a sentence is not in itself a finding about the gene and the disease.
glioma (28 papers, 2012 to 2025). A benign or malignant brain and spinal cord tumor that arises from glial cells (astrocytes, oligodendrocytes, ependymal cells). "The downregulated gene (MAP2) was mainly associated with tumor progression, which presented the characteristics of glioma-derived glial cells." (PMID 36085357, 2022). "Based on these findings, MAP2 appears to be a suitable diagnostic immunohistochemical marker for canine glioma, with strong potential of aiding in the diagnosis of astrocytoma based on the pattern of immunolabeling." (PMID 31803765, 2019). "MAP2 is a proven marker in human gliomas, consistently used for diagnostic and grading purposes, but its potential application in canine gliomas had not been explored to date." (PMID 31803765, 2019). "Microtubule-associated protein 2 (MAP2) is a proven marker of human glioma and is used to complement the diagnosis and its specific immunoreactivity pattern contributes to the differentiation of astrocytomas from other glial tumors." (PMID 31803765, 2019). "MAP2 is a proven marker of human glioma and is used for diagnostic and grading purposes." (PMID 33034957, 2020). "Moreover, miR-484, that is associated with poor prognosis in glioma, targets MAP2." (PMID 39002671, 2024). "Consistently, the hyperphosphorylation of microtubule‐associated proteins (MAP2 and MAP1B) revealed the activation of CAMK2G, GSK3A, GSK3B, MAPK8, and MAP4K6, corresponding to the active MAPK signaling pathway in glioma." (PMID 39716938, 2025). "It was reported that MAP2 interacts with Grb2 in glioma cells and that downregulation of MAP2 promotes the interaction between Grb2 and SOS." (PMID 39002671, 2024). "We have also validated tumor markers such as CLU and CST3 for Meningioma, ANXA1 and SOD2 in Glioma and MAP2 for Medulloblastoma." (PMID 34055594, 2021). "MAP2 cellular pattern of immunolabeling: All oligodendrogliomas (53/53; 100%) and undefined gliomas (12/12; 100%) had a combination of PNc and Ct staining." (PMID 31803765, 2019). "The overall statistical significance is difficult to interpret due to a limited and somewhat heterogeneous sample size; however, the IHC results presented herein suggest that MAP2 can be a valuable marker in the evaluation of canine glioma." (PMID 31803765, 2019). "MAP2 immunolabeling percentage: Equal numbers of gliomas were scored 3 (30/78; 38.5%) and 2 (30/78; 38.5%), while fewer scored 1 (18/78; 23%)." (PMID 31803765, 2019). "MAP2 scoring and neoplasm grading (low vs. high-grade) comparison: Most high-grade gliomas (18/41; 44%) were assigned a score of 2 when analyzing the MAP2 immunolabeling percentage, followed by 3 (16/41; 39%), and 1 (7/41; 17%)." (PMID 31803765, 2019). "The purpose of this study was to evaluate the expression of MAP2 in canine gliomas and determine if expression differences exist amongst oligodendroglioma, astrocytoma, and undefined gliomas." (PMID 31803765, 2019). "Thirty-five days after neural induction with CHIR99021 and forskolin, most of the glioma was converted into Tuj1-positive (~90%) or MAP2-positive (~80%) cells showing morphological diversity." (PMID 29161257, 2017). "Neuropathological assessments revealed tissue areas at the resection margins corresponding to TZ II, and postoperative CD34- and Map2 immunostaining confirmed these angiogenic hotspots to be occupied by glioma cells." (PMID 25609379, 2015). "The most notable lncRNA is LINC00599, which has DBSs in many NGS genes in most gliomas, including GABBR1, NRCAM, PTPRS, GLRB, GRIA4, GRIK3, and MAP2, and the most notable NGS gene is MAP2, which is associated with microtube assembly and regulated by multiple lncRNAs through the same DBS." (PMID 37693314, 2023). "The study demonstrates that MAP2 is expressed in canine gliomas and the pattern of expression can also be applied to help distinguish astrocytomas from oligodendrogliomas and undefined gliomas." (PMID 31803765, 2019).
glioma (continued). "Seventy-eight cases of canine glioma were evaluated for MAP2 expression by immunohistochemistry." (PMID 31803765, 2019). "By 14 dpi, more than 94% human glioma cells had been converted into MAP2-positive mature neurons." (PMID 31212628, 2019). "The objective of this study was to evaluate whether canine gliomas express MAP2 and to explore differences in the pattern of immunolabeling between different gliomas." (PMID 31803765, 2019). "The induction of MAP2 expression by NGN2/SOX11 in these glioma cells followed a similar pattern." (PMID 25321470, 2014). "Besides the proposed physiological role, MAP2–Grb2 interaction might be of interest in glioma pathophysiology." (PMID 39002671, 2024). "Thus, Imaging-Community-AMARETTO (Appendix Fig A1) identified THBS1 and MAP2 as novel master drivers across the three STAT3, AHR, CCR2, and OLIG2 communities that provide new insights into how these distinct key mechanisms are linked in glioma." (PMID 32383980, 2020). "It was suggested that MAP2 downregulation via miR-484 enhances Grb2–SOS interaction and subsequently upregulates ERK signaling pathway which leads to enhanced stemness of glioma cells." (PMID 39002671, 2024). "Second, some essential NGS genes such as MAP2 are regulated by different lncRNAs in different gliomas; meanwhile, important lncRNAs such as LINC00599 regulate different NGS genes in different gliomas." (PMID 37693314, 2023). "Nevertheless, the NGS genes PTPRS, MAP2, and CADM1 were expressed in most malignant cells across these gliomas, consistent with the observed neurological associations of these genes." (PMID 37693314, 2023). "The level of expression glioma-characteristic genes (e.g. CD34, GFAP, OLIG2, MAP2, MKI67, RBFOX3, SOX2, SYN; Suppl." (PMID 34545083, 2021). "Western blotting and immunostaining showed increase in molecular markers (GFAP, NeuF-H, β-tubulin-III, MAP2, Nestin, and GAP43) that confirmed the differentiation of glioma to astrocytes." (PMID 35011307, 2021). "Interesting avenues for further exploration with experimental validation studies include testing novel hypotheses of THBS1 and MAP2 as master regulators of shared mechanisms that involve macrophage infiltration, vascularization, tumorigenesis, invasion, stemness, and neurogenesis in glioma." (PMID 32383980, 2020). "To test this we performed qPCR on a selected panel of mRNAs of importance in glioma stem cell function: CD133, nestin, vimentin, TUJ1, GFAP and MAP2." (PMID 27564115, 2016). "By 21 dpi, >95% of NGN2/SOX11-infected glioma cells had been converted into neuron-like cells, based on the expression of either TUJ1 or MAP2." (PMID 25321470, 2014). "Parthenolide induced glioma cells to express neuronal markers NeuN, MAP2, SYP, and NEFL, but not astrocyte or oligodendrocyte markers." (PMID 39595109, 2024). "However, overexpression of miR-484 is considered as a poor prognosis factor for glioma patients, which targets MAP2 and activates ERK1/2 signaling resulting in the stemness characteristics of glioma cells." (PMID 33435549, 2021). "Consistent with U251, the time-course immunocytochemical analysis with neuronal markers DCX, TUBB3 and MAP2, showed that ASCL1 alone could also rapidly and efficiently reprogram U87 human glioma cells into neuron-like cells." (PMID 31212628, 2019). "Across the range of neural tumors, GFAP, OLIG-2 and MAP-2 are generally expressed by gliomas, while the neuronal marker synaptophysin is not." (PMID 25955030, 2015). "In GSLCs and glioma tissues, Sohlh1 expression was negatively correlated with the expression of GSLC markers, such as Nestin, CD133, CD44, SOX2 and OCT4, whereas Sohlh1 expression was positively correlated with the expression of GSLC differentiation markers, such as MAP2, GFAP and MBP." (PMID 40418209, 2025).
glioma (continued). "Also, the relationship between SNAP25 and MAP2 was not well distinguished as the low expression of MAP2 in U87Mcherry Lv-SNAP25 glioma cell-transplanted-xenograft may be simply related to the lack of tumor growth and size." (PMID 34490096, 2021).
schizophrenia (22 papers, 2016 to 2026). A major psychotic disorder characterized by abnormalities in the perception or expression of reality. "In schizophrenia, decreased expression of the microtubule-associated protein MAP2 and abnormalities in the DISC1 gene have been reported, potentially leading to dendritic morphological abnormalities and neurodevelopmental disorders." (PMID 41972553, 2026). "Deficient MAP2 immunoreactivity in postmortem brains is a hallmark of schizophrenia, and increasing MAP2 levels is a potential therapeutic approach for treating schizophrenia." (PMID 37298275, 2023). "For many years, altered immunoreactivity of microtubule associated protein-2 (MAP2) has been a hallmark found in the brains of individuals with schizophrenia." (PMID 35401110, 2022). "Reduced MAP2 immunoreactivity (MAP2-IR) has been reported in diverse brain regions in schizophrenia and has been described as a “molecular hallmark” of the disorder." (PMID 36187353, 2022). "This provided the first evidence indicating a potential pathogenic role for MAP2 phosphorylation in schizophrenia." (PMID 36187353, 2022). "Several postmortem studies have reported lower levels of immunoreactivity (IR) for microtubule-associated protein 2 (MAP2) in several cortical regions of individuals with schizophrenia (SZ)." (PMID 31462659, 2019). "There is evidence for reduced MAP2 expression or aberrant regulation in schizophrenia and psychiatric disorders, and MAP2 loss may indirectly affect GFAP+ve glia." (PMID 39951537, 2025). "Moreover, MAP2 expression has been associated with schizophrenia, which in the context of our study supports the animal models used." (PMID 39125900, 2024). "This indicates that at least one schizophrenia-associated MAP2 phosphorylation event may be capable of causing dendritic pathology in vivo." (PMID 36187353, 2022). "In summary, aberrant MAP2 phosphorylation in schizophrenia may both underlie the profound reductions in MAP2-IR observed postmortem and have direct consequences for neuronal structure and function." (PMID 36187353, 2022). "Dysregulated MAP2 phosphorylation has been implicated in a variety of neurological and psychiatric disorders, including Alzheimer’s disease and schizophrenia, highlighting the importance of understanding how phosphorylation modulates MAP2’s function." (PMID 40810115, 2025). "In the specific context of MAP2, recent studies have identified alterations in its phosphorylation status in brain samples obtained from individuals with schizophrenia." (PMID 39900676, 2025). "Understanding the functional consequences of these alterations can provide valuable insights into the role of MAP2 in schizophrenia and provide new possibilities for therapeutic interventions." (PMID 39532265, 2024). "Immunoreactivity of microtubule-associated protein 2 (MAP-2) has been shown to be reduced in the hippocampus and prefrontal cortex of postmortem tissue from patients with schizophrenia." (PMID 36340693, 2022). "Alternatively, our recent work in primary auditory cortex indicates that in schizophrenia, MAP2 is hyperphosphorylated, leading to changes in dendritic architecture." (PMID 36187353, 2022). "In support of this idea, several studies have suggested that the phosphorylation state of MAP2 is altered in schizophrenia." (PMID 36187353, 2022). "Other proteins relevant for the establishment of neuronal shape during development and often involved in the pathophysiology of schizophrenia, such as MAP-2, are also expressed by MDNCs." (PMID 34827371, 2021). "We have shown that the schizophrenia-associated DISC1-Boymaw fusion protein, which targets to mitochondria, localizes to mitochondria in MAP2 positive dendritic processes." (PMID 26553875, 2016). "Beyond these altered interactions with the cytoskeleton, MAP2S1782E might further induce these schizophrenia-related pathological changes by altering MAP2 interactions with other proteins involved in regulating dendritic function and structure." (PMID 39532265, 2024).
schizophrenia (continued). "Interestingly, novel gain-of-function interactions with PPM1L and KLHL8 nominated these as regulators of phosphoS1782 MAP2 abundance and potential therapeutic targets in schizophrenia." (PMID 39532265, 2024). "Moreover, in humans suffering from schizophrenia, increased dendritic arborization was found in the hippocampus compared to healthy humans when stained for MAP-2." (PMID 29673373, 2018). "In contrast, a neuronal marker, MAP2 expressions were decreased in schizophrenia brains." (PMID 27801899, 2016). "Therefore, MAP2-IR loss in schizophrenia does not appear to reflect reductions in mRNA/protein levels." (PMID 36187353, 2022). "Moreover, MAP2 mRNA levels are unchanged in the hippocampal formation in schizophrenia subjects." (PMID 36187353, 2022). "For example, MAP2 is not found at any schizophrenia risk loci and its protein levels are unaltered in schizophrenia tissue, yet it is hyperphosphorylated at multiple sites in schizophrenia and modeling just one of these sites induces a loss of dendritic spines." (PMID 34335181, 2021). "Many studies of altered WMN density in schizophrenia have focused on three key markers, NADPH, MAP2 and NeuN, the latter because it detects all mature neurons." (PMID 31285426, 2019). "Control organoids showed organized ventricle zones with SOX2-expressing progenitor cells and MAP2-expressing neuronal cells at the cortical layer, while schizophrenia patients had a larger area covered by SOX2 progenitors, also showing MAP2 distribution throughout the organoid." (PMID 36451159, 2022). "While lower tissue pH (a possible indicator of brain health prior to death) was correlated with lower MAP2-IR in one study, this effect did not account for reductions present across the cortex in schizophrenia." (PMID 36187353, 2022). "Interestingly, we detected increased expression of GFAP, an astrocyte marker, decreased expression of MAP2, a neuronal marker, and elevated ratio of GFAP/MAP2, in postmortem brains of patients with schizophrenia." (PMID 27801899, 2016). "While no prior studies have identified specific roles of PPM1L and KLHL8 in schizophrenia, our data nominate PPM1L and KLHL8 as potential regulators of MAP2 phosphorylation levels, and thus as novel targets for further exploration to reverse schizophrenia-related hyperphosphorylation of MAP2." (PMID 39532265, 2024). "Moreover, a lack of MAP2 immunoreactivity has also been described in brain samples from individuals with schizophrenia, which did not correspond with the results of MAP2 detection by proteomic techniques where no decrease in MAP2 expression was detected in those same samples." (PMID 39900676, 2025).
Alzheimer disease (21 papers, 2005 to 2025). A progressive, neurodegenerative disease characterized by loss of function and death of nerve cells in several areas of the brain leading to loss of cognitive function such as memory and language. "For examining spine morphology, co-immunostaining for MAP2 and Drebrin, a spine protein that has been implicated in memory loss in Alzheimer’s disease, was analyzed in primary neuronal cultures." (PMID 33546775, 2021). "Depletion of MAP2 has been associated with a Lewy body variant of Alzheimer’s disease, whereas colocalization of MAP2 with α-synuclein in Lewy bodies was shown in Parkinson’s disease." (PMID 30884818, 2019). "Microtubule-associated protein 2 (MAP2) is found in post-synaptic dendrites and is functionally similar to tau protein, whose abnormal phosphorylation is another key component in Alzheimer's disease." (PMID 25329999, 2014). "Furthermore, decreased expression of MAP-2 and resulting dystrophic neurites can be found associated with impaired learning and memory formation in Alzheimer’s disease models." (PMID 36340693, 2022). "Bin Li and colleagues showed that separating normal brain tau and MAP2, an aberrantly hyperphosphorylated tau protein, from the cytoplasmic lysate of Alzheimer’s disease brains (AD P-tau) inhibits microtubule network construction and causes disruptions." (PMID 39640295, 2024). "There are also several reports of decreases in MAP2 levels in Alzheimer's disease and Parkinson's disease." (PMID 27489535, 2016). "It has been reported that in the brains of Alzheimer's diseases, the levels of MAP2 are usually decreased." (PMID 22272295, 2012). "Stable neuronal Map2 expression has previously been demonstrated to be altered in the aging process as well as neurological disorders such as Alzheimer's disease and Downs Syndrome." (PMID 22606319, 2012). "NF-H and MAP2 are substrates of the Ca2+-dependent cysteine protease, calpain, the levels of calpain are increased in the brains of patients with Alzheimer's disease." (PMID 18706097, 2008). "Apolipoproteins E, E4, and J, and microtubule-associated protein 2 have been associated with CAA syndromes and Alzheimer's disease." (PMID 16321154, 2005). "Alzheimer disease P-tau sequesters normal tau, MAP1, and MAP2 and disassembles microtubules and that the dephosphorylation of AD P-tau eliminates this toxic property." (PMID 23966973, 2013). "Whereas Tau is widely accepted as a pathoetiological factor in human tauopathies, including Alzheimer's disease (AD), it is not known whether there is a relationship between MAP2 and tauopathy." (PMID 24587039, 2014).